SIGLEC15 (sialic acid binding Ig like lectin 15)
Diseases named in the same sentence as SIGLEC15 in open-access papers (continued):
Sharing a sentence is not in itself a finding about the gene and the disease.
cancer (continued). "The groundbreaking research work about SIGLEC15 has raised it as a potential promising target in cancer immunotherapy." (PMID 36159823, 2022). "Siglec15 suppresses T-cell activation, and an antibody against Siglec15 has shown notable potential in cancer immunotherapy." (PMID 35232979, 2022). "Our findings brought to light that PTX3 had a close and positive association with most ICIs (CD274, CTLA4, HAVCR2, LAG3, PDCD1, PDCD1LG2, TIGIT, and SIGLEC15) in TCGA cancers, except TGCT." (PMID 36139597, 2022). "Remarkably, the IRS was negatively related to Siglec15, but positively related to the pan-cancer T cell inflamed score." (PMID 33537076, 2021). "In this study, we performed a pan-cancer analysis of the expression patterns and immunological role of Siglec15." (PMID 33537076, 2021). "Siglec15 was overexpressed TME-specifically in various cancers, which implies fewer side effects of anti-Siglec15 treatment." (PMID 33537076, 2021). "The results suggested that UBE2C expression was positively associated with the immune checkpoint-related genes in 31 cancers, which mainly included CD274, CTLA4, HAVCR2, LAG3, PDCD1, PDCD1LG2, SIGLEC15, and TIGIT." (PMID 34858987, 2021). "It has been reported that SIGLEC15 overexpression is correlated with favorable or unfavorable outcomes in different types and subtypes of cancer." (PMID 34722496, 2021). "As anticipated, Siglec15 emerged as a prognostic biomarker in various cancers, even though its prognostic value was variable in different cancers." (PMID 33537076, 2021). "Here, we noted that Siglec15 was negatively correlated with the activities of several steps of the cancer immunity cycle." (PMID 33537076, 2021). "Lately, Siglec‐15 has been reported to act as an novel immune checkpoint molecule and could be identified as a suitable candidate for cancer immunotherapy." (PMID 38725348, 2024). "Siglec15 plays an important role in maintaining immune homeostasis, and its dysregulation may lead to cancer progression by suppressing T cells through different pathways." (PMID 37325664, 2023). "We also firstly revealed the m6A methylation regulator relationship with SIGLEC15; regulating the expression of SIGLEC15 via methylation in cancer may be another road." (PMID 36159823, 2022). "In addition, we studied the relationship between the expression of KCC2 (SLC12A5) and NKCC1 (SLC12A2) in pan-cancer and immune checkpoint genes, including SIGLEC15, IDO1, CD274, HAVCR2, PDCD1, CTLA4, LAG3, and PDCD1LG2." (PMID 35372048, 2022). "Specifying the role of SIGLEC15 in THCA could represent a potential next-generation cancer immunotherapy option for patients." (PMID 36159823, 2022). "Rationale: Siglec15 is an emerging target for normalization cancer immunotherapy." (PMID 33537076, 2021). "We further explored the correlation between YTHDC2 and eight immune checkpoint‐related genes and found that YTHDC2 was significantly associated with the expression of SIGLEC15, IDO1, CD274, HAVCR2, PDCD1, CTLA4, LAG3 or PDCD1LG2 in almost all types of cancers except for CESC and TGCT." (PMID 34312987, 2021). "The pan-cancer overexpression pattern of Siglec15 prompted us to explore its prognostic value." (PMID 33537076, 2021). "In addition, Siglec15 was negatively correlated with the pan-cancer T cell inflamed score (R = -0.38, P < 0.001)." (PMID 33537076, 2021). "Nevertheless, we noted that Siglec15 was negatively correlated with TMB and MSI in several cancers, suggesting that Siglec15 may reflect cancer immunogenicity in these cancers." (PMID 33537076, 2021). "SIGLEC15 has been shown to be a novel target for normalized cancer immunotherapy." (PMID 34722496, 2021). "Pan-cancer analyses aimed at depicting the immunological role of Siglec15 are critical in determining the types of cancers that may benefit from anti-Siglec15 immunotherapy." (PMID 33537076, 2021). "Interestingly, the activity of recognition of cancer cells by T cells (Step 6) was downregulated in the low-Siglec15 group." (PMID 33537076, 2021).
cancer (continued). "These contradictory results in different types of cancer reveal that the complexity and heterogeneity in tumors and that Siglec15 and PD-L1 may be simultaneously regulated by other molecules in COAD; this line of research needs to be further investigated in future studies." (PMID 37859817, 2023). "However, the significance of Siglec15 in cancer is uncertain." (PMID 37859817, 2023). "Finally, BLCA was identified as the ideal cancer for anti-Siglec15 immunotherapy." (PMID 33537076, 2021). "As Chen and colleagues have shown, Siglec15 overexpression has been documented in numerous human cancers and its expression is mutually exclusive of PD-L1, suggesting that it may be a potential therapeutic target for patients who are refractive to anti-PD-1/PD-L1 checkpoint blockade therapy." (PMID 34253827, 2021). "Notably, a combination of anti-Siglec15 and cancer immunotherapy may be a more effective strategy than monotherapy." (PMID 33537076, 2021). "Cancer cells can exploit immune checkpoints to evade immune responses, and the ADGRG6-high group displayed increased levels of CD274/PDL1 and SIGLEC15 expression." (PMID 40226617, 2025). "We examined the relationship between EIF5A2 and immune checkpoints using Spearman analysis and found that EIF5A2 was correlated with CD274, PDCD1LG2, and HAVCR2 in the majority of cancers and PDCD1, CTLA4, LAG3, SIGLEC15, and TIGIT in some tumors." (PMID 40964657, 2025). "We analyzed the expression profile of COMMD2 gene and ICGs (CD274, CTLA4, HAVCR2, LAG3, PDCD1, PDCD1LG2, SIGLEC15, and TIGIT) at a pan‐cancer level." (PMID 36205192, 2023). "The key immune checkpoints (CD274, CTLA-4, HAVCR2, LAG3, PDCD1, PDCD1LG2, SIGLEC15, and TIGIT) also had a significant relationship with DTYMK expression in approximately 20 kinds of cancers, except in MESO, PCPG, and UCS." (PMID 36094557, 2022). "Afterward, we evaluated the link between DTYMK expression and key immune checkpoints (CD274, CTLA-4, HAVCR2, LAG3, PDCD1, PDCD1LG2, SIGLEC15, and TIGIT) expression levels in pan-cancer." (PMID 36094557, 2022). "We found that the expression level of GRWD1 was positively correlated with the expression levels of immune checkpoint-related genes (CD274, CTLA4, HAVCR2, LAG3, PDCD1, PDCD1LG2, SIGLEC15, and TIGIT) in most types of cancer, especially in STAD." (PMID 34616846, 2021). "In summary, the overexpression pattern of Siglec15 is TME specific, which demonstrates the potential of Siglec15 as a target for normalized cancer immunotherapy." (PMID 33537076, 2021). "Furthermore, in pan-cancer, TRPM6 was negatively correlated with CD274, LAG3, PDCD1, and SIGLEC15, and showed significant differences (P < 0.01)." (PMID 41562086, 2025). "The GEPIA database described the expression status of Siglec‐15 in 31 human cancer samples compared with that of in noncancerous samples." (PMID 38725348, 2024). "The qPCR test with 16 LUAD samples showed substantially elevated expression of Siglec‐15 in cancer tissues than that in noncancerous tissues." (PMID 38725348, 2024). "Besides, our research manifested the correlation of SLC7A11 with 8 IC genes, namely CD274 (also known as PD-L1), HAVCR2, LAG3, SIGLEC15, PDCD1LG2, CTLA4, PDCD1, and TIGIT in 33 cancer types." (PMID 36267158, 2022). "We further explored the correlation between the expression of LIPT1 and eight immune checkpoints (PD-L1, CTLA4, HAVCR2, LAG3, PDCD1, PDCD1LG2, SIGLEC15, and TIGIT), and found that LIPT1 levels were correlated with the expressions of these immune checkpoints, especially PD-L1, in most cancer types." (PMID 35837286, 2022). "The immunosuppressive effect of Siglec15 in TME is the most obvious in BLCA, which suggests that BLCA may be a suitable candidate cancer type for anti-Siglec15 immunotherapy." (PMID 33537076, 2021). "Meanwhile, Siglec15 was positively related to PD-L1, PD-1, CTLA-4, and LAG-3 in most cancers." (PMID 33537076, 2021).
cancer (continued). "Three months later, Lieping Chen group identified SIGLEC15 as a critical immune suppressor and its expression was mutually exclusive to PDL1, which implicated its potential therapeutic value in cancer patients especially for those who failed to response to anti-PDL1 therapy." (PMID 34717291, 2021). "However, it is critical to note that the potential of Siglec15 as a broad-spectrum therapeutic target was not validated in pan-cancers before initiating this phase II clinical trial." (PMID 33537076, 2021). "We hypothesize that Siglec15 designs a non-inflamed TME in BLCA based on the evidence that Siglec15 negatively correlated with immunomodulators, TIICs, cancer immunity cycles, immune checkpoints, and T cell inflamed score." (PMID 33537076, 2021). "However, we found that Siglec15 may exert an immunosuppressive function by comprehensively downregulating the expression of critical immunomodulators such as CXCL9, CXCL10, and CXCR3, and subsequently downregulating the activities of the cancer-immunity cycle." (PMID 33537076, 2021). "Therefore, Siglec15 is considered a promising new target for normalization cancer immunotherapy independent of the PD-1/PD-L1 pathway, and targeting Siglec15 may be an effective alternative therapy for patients who do not respond to PD-1/PD-L1 antibodies 16-18." (PMID 37859817, 2023). "Likewise, a prior treatment option for BLCA with high Siglec15 expression was to transform a non-inflamed TME into an inflamed TME and consequently trigger an anti-cancer immune response." (PMID 33537076, 2021).
adenocarcinoma (1 paper, 2020). A common cancer characterized by the presence of malignant glandular cells. "However, bioinformatics analysis clearly demonstrates the absence of changes in SIGLEC15 mRNA content in major adenocarcinomas, either treated or untreated with chemotherapeutics." (PMID 33171937, 2020).
SIGLEC15 also shares sentences with these, for which no sentence is quoted: head and neck squamous cell carcinoma (4 papers); breast invasive carcinoma (3); prostate adenocarcinoma (3); uterine corpus endometrial carcinoma (3); bladder urothelial carcinoma (2); ovarian serous cystadenocarcinoma (2); pancreatic adenocarcinoma (2); triple-negative breast carcinoma (2); acute lymphoblastic leukemia (1); acute myeloid leukemia (1); brain cancer (1); cervical squamous cell carcinoma (1); clear cell renal carcinoma (1); colorectal adenocarcinoma (1); endocervical adenocarcinoma (1); esophageal carcinoma (1); gastric cancer (1); infectious disease (1); Kawasaki disease (1); liver cancer (1); lung squamous cell carcinoma (1); lymph node metastasis (1); Obesity (1); pediatric cancers (1); prostate carcinoma (1); skin cutaneous melanoma (1); spinal cord injury (1); testicular germ cell tumor (1); thymoma (1).